BRCA1 (BRCA1 DNA repair associated)
Diseases named in the same sentence as BRCA1 in open-access papers (continued):
Sharing a sentence is not in itself a finding about the gene and the disease.
ovarian carcinoma (continued). "Evidence of X-linkage is not inconsistent with the prevailing autosomal dominant BRCA1/2 with polygenic weak variant effects model for ovarian cancer." (PMID 29447163, 2018). "The most common type of ovarian cancer noted in these BRCA1 or 2 carriers is HGSC." (PMID 30424539, 2018). "In addition to the presence of either BRCA1 or BRCA2 mutations in breast and/ovarian cancer patients, there are reports of patients being double heterozygous for both BRCA1 and BRCA2 mutations." (PMID 29459887, 2018). "This increase may be related to the common BRCA1 gene for both early-onset ER-negative breast cancer and ovarian cancer." (PMID 29556910, 2018). "The spectrum and frequency of BRCA1/2 mutations between ovarian cancer patients have not yet been studied in the region of South-East Poland." (PMID 29492181, 2018). "The majority of their inherited risk would be due to a discoverable BRCA1/2 mutation and the negative test will greatly reduce their risk of breast and ovarian cancer, due to the high sensitivity of current BRCA testing." (PMID 27796713, 2017). "Thus, with the list of associated gene mutations evolving, more women can be expected to carry some mutation pre-disposing them to ovarian cancer and overall will exceed the 15% of all ovarian cancers attributed to BRCA1 and BRCA2." (PMID 28406427, 2017). "Besides the well described tumor suppressor function of BRCA1 in breast and ovarian cancers, more recent research also demonstrates an important role for BRCA1 in suppression of endothelial dysfunction and atherosclerosis." (PMID 28698603, 2017). "Following this, paired phase II studies were then carried out which confirmed cell killing effect and demonstrated dose response in BRCA1/2 mutant breast and ovarian cancers, with better patient outcomes observed for patients with platinum sensitive compared to platinum resistant disease." (PMID 28829366, 2017). "A similar likelihood of progression-free survival was shown after five years in a large cohort of women with FIGO stage III or IV epithelial ovarian cancer but these studies did not take BRCA1/BRCA2 mutation status into account." (PMID 28780755, 2017). "FANCM mutation testing in women with HGSOC might also have clinical utility through targeted treatment with Poly (ADP-ribose) polymerase (PARP) inhibitors, which are currently being evaluated in women with BRCA1 and BRCA2 associated ovarian cancer." (PMID 28881617, 2017). "We studied a group of 18 families with hereditary breast and ovarian cancer by family history and age of presentation criteria (<55 years old) and performed complete exons and partial intron sequencing of BRCA1/2 genes and screening for large rearrangements by MLPA." (PMID 28944232, 2017). "We hypothesized that BAP1-mutant MPM would require PARP1 for survival, similar to the BRCA1/2 mutant breast and ovarian cancers." (PMID 28756516, 2017). "Who raises this issue and when it is raised during the consultation depends on many factors, which may include the patient’s pre-test understanding of BRCA1/BRCA2 mutation risks, family history and response to ovarian cancer treatment." (PMID 28780755, 2017). "The present meta-analysis with the largest number of patients investigated both survival (OS) and progression outcomes (PFS) for ovarian cancer, incorporating not only the general BRCA mutation status but also two subtypes, including BRCA1 and BRCA2 mutation status." (PMID 27690218, 2017).
ovarian carcinoma (continued). "Sporadic ovarian cancer showed significantly reduced levels, rather than complete loss, of BRCA1 expression." (PMID 28270171, 2017). "Among women at high risk of breast and ovarian cancer who have previously tested negative for pathogenic BRCA1 and BRCA2 mutations, we identified three groups of women who should be considered for subsequent multi-gene panel testing." (PMID 28281021, 2017). "We identified three pathogenic PALB2 mutations among 460 BRCA1/2-mutation negative breast and/or ovarian cancer patients." (PMID 28279176, 2017). "In addition to BRCA1 and BRCA2, many other proteins are involved in the HR repair process of double-strand DNA breaks and are implicated in hereditary breast and ovarian cancer susceptibility." (PMID 28073364, 2017). "Mutations in BRCA1 and BRCA2 genes are associated with elevated risk of breast and ovarian cancer." (PMID 28729482, 2017). "In five of the 51 ovarian cancer patients without a germline BRCA1 or BRCA2 mutation included in this study, a somatic, pathogenic mutation affecting BRCA1 or BRCA2 was encountered." (PMID 27767231, 2017). "The willingness amongst oncologists to offer population-based genetic testing to all adult female patients may reflect the move towards mainstreaming BRCA1/2 genetic testing within ovarian cancer care." (PMID 29246147, 2017). "Downregulation of BRCA1 is frequent ( > 72%) in high-grade ovarian cancers." (PMID 28008141, 2017). "Here, we show that this combined approach allows the rapid and reliable detection of both germline and somatic aberrations affecting BRCA1 and BRCA2 in DNA derived from FFPE OCs, enabling improved hereditary cancer risk assessment and clinical treatment of ovarian cancer patients." (PMID 27767231, 2017). "Lifetime risks for ovarian cancer are up to 44% and 27% for BRCA1 and BRCA2, respectively." (PMID 28157161, 2017). "However, this study aimed on the identification of reversion BRCA1/2 mutations that could be responsible for acquiring the chemotherapy resistance, not on the overall screening of both germline and somatic alterations in a large cohort of unselected ovarian cancer patients." (PMID 29254167, 2017). "Second, individuals who have previously received limited BRCA1 and BRCA2 gene testing may still harbor a genetic risk of breast and/or ovarian cancer and should be considered for multi-gene panel testing including large rearrangement testing." (PMID 28281021, 2017). "PARP inhibitors have therefore been approved for use in advanced ovarian cancer patients harboring germline BRCA1/2 mutations in both the USA and Europe, but not in Japan yet." (PMID 29383094, 2017). "While phase I/II clinical trials with olaparib have reported impressive objective response rates in patients with advanced BRCA1/2 mutation ovarian cancer, not all patients achieve the same level of benefit to olaparib." (PMID 28454085, 2017). "In summary, our study confirmed two PALB2 recurrent mutations, c.172_175delGA and c.509_510delGA, in BRCA1/2-mutation negative breast and/or ovarian cancer patients from Poland." (PMID 28279176, 2017). "The index patient with a duplication of BRCA1 exon 4–6 was diagnosed at the age of 67 with invasive serous epithelial ovarian cancer, had 2 close blood relatives with breast and/or epithelial ovarian cancer and also had 2 close blood relatives with cancers other than breast or ovary." (PMID 28351343, 2017). "However, it is suggested a deeper exploration of the relationship between genetic changes and protein expression of BRCA1/2 in sporadic ovarian cancer." (PMID 28187748, 2017). "Afterwards, to analyze the effects that exosomes isolated from cancer patients’ sera had on the behaviour of exposed BRCA1-KO cells, we extracted exosomes from the sera of patients with colorectal cancer, hepatocellular carcinoma, pancreatic cancer and ovarian cancer." (PMID 28854931, 2017).
ovarian carcinoma (continued). "One possibility would be to assume that women with BRCA1 mutations would not be offered RRSO until their cumulative risk of ovarian cancer approaches or exceeds 2.8%." (PMID 28376175, 2017). "The only isolated population subgroup that might benefit from ovarian cancer screening tests is patients with mutations within the BRCA1 and BRCA2 genes and burdened by a family history of ovarian cancer." (PMID 28182133, 2017). "We hypothesized that BAP1-mutant mesothelioma might be addicted to PARP1-mediated DNA repair pathways, similar to the BRCA1/2-mutant breast and ovarian cancers." (PMID 28756516, 2017). "Most importantly, although BRCA1 deletion and mutation are observed in a subset of ovarian cancers, they are mostly absent in samples with USP13 amplification." (PMID 28569838, 2017). "Inhibition of AURKA activity also decreased the expression of BRCA1/2 in ovarian carcinoma cells." (PMID 28881569, 2017). "Supporting this hypothesis, previous studies have demonstrated elevated rates of pathogenic mutations in genes other than BRCA1 and BRCA2 (6–7%) among women with ovarian cancer." (PMID 28281021, 2017). "Taking into account the well-established association of PALB2 with BC and its close relationship with BRCA1 and BRCA2, it is legitimate to inquire whether mutations in this gene would enhance the risk for ovarian cancer (OC)." (PMID 28858227, 2017). "Besides olaparib, rucaparib successfully obtained FDA approval in December 2016 for treatment of patients with germline or somatic BRCA1/2-mutant ovarian cancers that have progressed on two or more lines of chemotherapy." (PMID 28829366, 2017). "Mutations in BRCA1 and BRCA2 increase the risk of female breast and ovarian cancers." (PMID 28069070, 2017). "In premenopausal BRCA1 mutation carriers, significantly lower serum HE4 levels were observed in comparison to patients with ovarian cancer (P = 0.0000), other gynecological cancers (P = 0.0002), uterine myomas (P = 0.0021), noncancer ovarian cysts (P = 0.0000), and adnexitis (P = 0.0035)." (PMID 28182133, 2017). "The aim of the present study was to investigate the contribution of PALB2 germline mutations in a group of 460 BRCA1/2-mutation negative breast and/or ovarian cancer patients and identify the optimal panel of recurrent mutations for genetic screening of PALB2." (PMID 28279176, 2017). "The corresponding ovarian cancer risks are 16–68% for BRCA1 carriers and 11–30% for BRCA2 carriers." (PMID 28985766, 2017). "Heterozygous BRCA1 and BRCA2 mutations increase the risk of breast and ovarian cancers." (PMID 28729482, 2017). "In the present study, a significantly lower rate of BRCA1 promoter hypermethylation in recurrent ovarian cancer compared to primary tumors could be demonstrated." (PMID 29137324, 2017). "Methylation of DNA repair genes during tumour development might lead to drug sensitivity, as disseminated single ovarian cancer tumor cells with functional BRCA1 have a higher chemoresistance and might be selected for during therapy." (PMID 29137324, 2017). "We found that ovarian cancer patients with BRCA1-mutation had significantly longer OS than non-carriers, regardless of study quality, sample size, research center or duration of follow-up." (PMID 27690218, 2017). "Although the role of BRCA2 has been established in breast and ovarian cancer, the K3326* variant is considered to be benign by commercial testing and therefore was not identified in the initial BRCA1/BRCA2 screening." (PMID 28591191, 2017). "Low or no expression of BRCA1 in breast and ovarian cancers is associated with a good clinical response to treatment with platinum therapies and PARP1 inhibitors." (PMID 29021870, 2017). "Therefore, the genetic analysis of BRCA1/2 is important for prevention, therapeutic decision-making, and proper management of breast and ovarian cancer patients." (PMID 29383094, 2017).
ovarian carcinoma (continued). "If and when risk-reducing breast surgery in BRCA1/BRCA2 carriers with a previous diagnosis of ovarian cancer is appropriate is not easily answered by current research evidence." (PMID 28780755, 2017). "We evaluated the frequencies of PALB2 germline mutations in 460 BRCA1/2-mutation negative breast and/or ovarian cancer patients." (PMID 28279176, 2017). "Interestingly, in Potapova’s (2008) study, the methylation frequency observed in breast and ovarian cancers (hereditary and sporadic) was described as similar to the one observed in BRCA1 promoter region." (PMID 28858227, 2017). "BARD1 gene mutations affect the function of the BRCA1/BARD1 heterodimer, which may affect cancer progression, particularly in breast and ovarian cancer." (PMID 28794477, 2017). "The current study indicates that founder BRCA1 mutations reported in Polish breast/ovarian cancer patients do not contribute to increased GC risk." (PMID 26779294, 2016). "Mutations in BRCA1 and BRCA2 genes confer a high risk of both breast and ovarian cancer." (PMID 27876019, 2016). "BRCA1 and BRCA2 mutations account for a considerable proportion of Chinese hereditary breast/ovarian cancer patients, and the penetrance of these two genes should be investigated because such investigations will be very important for the development of a preventive treatment strategy in China." (PMID 26852015, 2016). "Furthermore, we have demonstrated that this results in elevated levels of expression of Ubc9 both at the RNA as well as protein levels in these BRCA1 Ubc9 mutant UWB1.289 ovarian cancer and HCC1937 TNBC cells." (PMID 28164176, 2016). "Beyond the high penetrance BRCA1/2 genes, mutations of several cancer susceptibility genes, including ATM, CHK2 and PALB2, have been shown to associate, with a moderate penetrance, with familial breast and/or ovarian cancers." (PMID 27599564, 2016). "More than a half of the tested breast/ovarian cancer patients originating from FVG and neighboring geographic areas of Veneto (Italy) and Istria (Slovenia and Croatia) were found to be carrier of one of the 8 BRCA1 or BRCA2 recurrent mutations." (PMID 26852130, 2016). "Younger patients with ovarian cancer were seen among BRCA1 mutation carriers in comparison with noncarriers (median age 47 vs 56, respectively, p = 0.004)." (PMID 26753012, 2016). "Concomitantly decreased BRCA1/2 expression might predict effective response of ovarian cancer cells to the combination treatment." (PMID 26909613, 2016). "In addition, in another study performed in our city, a few patients with ovarian cancer were enrolled for entire BRCA1/2 gene sequencing." (PMID 27914478, 2016). "In addition, expression levels of phospho-BRCA1 (Ser1524) and BRCA1 as a key regulated protein in DNA double-strand repair mechanism and homologous recombination were diminished in si-Cdk1 transfected ovarian cancer cell lines, in a time-dependent manner." (PMID 27385216, 2016). "Among the 68 patients with informative family history for breast and/or ovarian cancer, 35.5% with and 13.5% without any affected first and/or second-degree relatives were BRCA1/2 mutations carriers." (PMID 27914478, 2016). "It is perhaps possible to suggest that as a prognostic for outcome following therapy in ovarian cancer, BRCA1-IRIS expression could be measured." (PMID 27489859, 2016). "In this regard, it is relevant that mammalian cells lacking the major hereditary breast/ovarian cancer predisposition genes BRCA1 or BRCA2 or other cancer predisposition HR genes reveal a bias towards LTGC." (PMID 27832076, 2016). "For example, mutations in BRCA1 and BRCA2 have long been known to confer cancer susceptibility and women with a germ-line heterozygous mutation have an overall increased lifetime risk of developing breast and ovarian cancers." (PMID 27788678, 2016).
ovarian carcinoma (continued). "Germline (g) mutations in either the BRCA1 or BRCA2 genes render individuals at high life-time risk of breast and ovarian cancer and these subsequent cancers may have HRR deficiency (HRD)." (PMID 27002934, 2016). "BRCA1 and BRCA2 mutations are responsible for hereditary breast and ovarian cancer, but they also confer an increased risk for the development of rarer cancers associated with this syndrome, namely, cancer of the pancreas, male breast, peritoneum, and fallopian tube." (PMID 27532258, 2016). "Notably, ovarian cancer cells responsive to the PI3K/PARP combination displayed decreased BRCA1/2 expression upon drug treatment." (PMID 26909613, 2016). "Nevertheless, a recent report has shown that immunohistochemical expression of BRCA1 could predict the genetic status of BRCA1 in ovarian carcinoma." (PMID 27643881, 2016). "Therefore, it will be important to invest in resources and approaches that will change how ovarian cancer and other solid tumors with BRCA1/2 involvement are managed and prevented, to improve the current paradigm of care." (PMID 27242959, 2016). "An immediate improvement to treatment opportunities would be to offer systematically genetic testing for BRCA1/2 mutation to all HGSOC, although it has been reported that 20% of women with ovarian cancer in community hospital settings were referred for genetic testing." (PMID 27242959, 2016). "Interestingly, BRCA1 status appeared to be of clinical value as a prognostic factor for OS in ovarian cancer patients." (PMID 26753012, 2016). "The 4q32.3 locus is associated with ovarian cancer risk in BRCA1 but not in BRCA2 mutation carriers or the general population, while the opposite is true for the locus 17q11.2." (PMID 27463617, 2016). "However, seven women with breast or ovarian cancer and previous BRCA1/2 testing were found to have a positive BRCA1/2 finding on an NGS panel in our laboratory." (PMID 26681312, 2016). "Carriers of any mutation of the BRCA1 gene with ovarian cancer had better survival at two years in comparison with noncarriers." (PMID 26753012, 2016). "Thus, PB which is reported earlier to have a specific cytotoxicity in BRCA1-defective ovarian cancers, is found in this study to possess the ability to target BRCA1-defective BCSCs as well." (PMID 27229859, 2016). "Conservative methods of prevention also failed to reduce the mortality due to ovarian cancer in a group of high-risk patients – carriers of the BRCA1 or BRCA2 gene mutations." (PMID 26928677, 2016). "Of note, six patients with cancer had additional risk factors (family history of ovarian cancer, BRCA1/2 mutations, or prior atypia), compared to none in the control group." (PMID 27449059, 2016). "Taken together, these results indicate that BRCA1/2 expression may be used to predict the efficacy of drug treatment in ovarian cancer cells." (PMID 26909613, 2016). "Another frequent mutation detected in our ovarian cancer patients was the one commonly found in the Ashkenazi Jewish, BRCA1 c.5266dupC (5382insC), however none of them reported Jewish ancestry." (PMID 27914478, 2016). "One study examined the development of chemoresistance in ovarian cancer cell lines and found that cell lines with functional BRCA1 developed paclitaxel resistance more quickly than cell lines with non-functional BRCA1 (due to gene silencing by hypermethylation)." (PMID 27191893, 2016). "For high-risk variants, such as mutations in BRCA1, this is not true as the population of higher risk carriers is depleted across the decades by death from breast and ovarian cancers." (PMID 26960971, 2016).